CCND1 (cyclin D1)
Diseases named in the same sentence as CCND1 in open-access papers (continued):
Sharing a sentence is not in itself a finding about the gene and the disease.
melanoma (continued). "Overexpression of cyclin D1 is mainly related to human tumorigenesis and metastasis progression, eventually affecting the development of several human cancer types, such as parathyroid adenoma, breast cancer, colon cancer, prostate cancer, lymphoma and melanoma." (PMID 33917849, 2021). "All types of CCND1 translocations result in overexpression of CCND1, a proto-oncogene that regulates cell cycle transition from G1 to S phase and is often overexpressed or amplified in numerous cancers, including breast, lung, melanoma, and oral squamous cell carcinomas." (PMID 34888236, 2021). "In this study, we aimed to explore the relationship of CCND1 copy number alteration and cyclin D1 protein expression in acral melanoma, and to determine whether anti-cyclin D1 IHC may be used as a surrogate for direct evaluation of increase in CCND1 copy number." (PMID 34225728, 2021). "Furthermore, the CCND1 gene gain was the most sensitive criterion of melanomas in this cohort." (PMID 32393283, 2020). "Additionally, thin primary melanomas leading to the development of metastatic disease were specifically analysed in order to explore the potential role of cyclin D1 later in the process of invasion and metastasis development, hence re‐evaluating its potential as a prognostic marker." (PMID 32374893, 2020). "Therefore, in the light of the polyhedral functions of cyclin D1, the inhibition of cancer growth and metastatic diffusion induced by these compounds in melanoma cells, could be also mediated by the inhibition of cyclin D1 expression." (PMID 31801187, 2019). "Univariate Cox analysis suggested thatCdk4 gain, Ccnd1 gain, P16INK4a loss or other stochastic combinations might not be of prognostic significance for melanoma patients." (PMID 31358010, 2019). "Therefore, the expression of cyclin D1, a key regulator mainly of the G1/S but also of the G2/M phases, was analysed by western blot experiments on A375, HT-144 and M74 melanoma cells treated as reported for 24 h, 48 h and 72 h with (Bu2Sn)2TPPS and with (Bu3Sn)4TPPS." (PMID 31801187, 2019). "The inactivation of p16CDKN2A is due to either genetic (mutations, deletions) or epigenetic (promoter methylation) mechanisms, whereas the amplification of CCND1 is particularly frequent in melanomas negative for BRAF/NRAS mutations, in chronically sun-exposed skin areas." (PMID 30218391, 2018). "Functionally, upregulation of MEG3 inhibited melanoma cell proliferation, invasion, and migration, enhanced melanoma cell apoptosis, arrested melanoma cell cycle, and regulated the expression of E-cadherin, N-cadherin, and cyclin D1 by regulating CYLD expression mediated by sponging miR-499-5p." (PMID 29808164, 2018). "MAPK pathway activation and cell cycle dysregulation are general hallmarks of melanoma resulting from aberrations in cell proliferation, deficiency of the retinoblastoma protein (pRb), mutations in CDK4, and overexpression of cyclin D1 following resistance to BRAF inhibition." (PMID 29541385, 2018). "Therefore, we hypothesized that RGS4 directly induced inactivation of E2F1 under the regulation of Cyclin D1 or AKT in melanoma." (PMID 29108247, 2017). "Thus, Gö6976 treatment inhibits cyclin D1 expression in M2 melanoma cells." (PMID 28056869, 2017). "Furthermore, we aimed to deepen the knowledge of the mechanism responsible for the down-proliferative response of melanoma cells after exposure to αMSH, by analyzing cell proliferation and protein levels of p27, p21, cyclin D1 and E, as typical proliferation modulators." (PMID 29020973, 2017). "Interestingly, we observed a significant increase in p21 and Cyclin D1 in the TAN skin of un-irradiated trigenic RXRαep−/− mice, suggesting that those changes might be consequences of loss of functional RXRα in the melanoma microenvironment." (PMID 29121869, 2017).
melanoma (continued). "Furthermore, mutation or overexpression of CDK4, combined with amplification of cyclin D1, has been implicated in resistance to BRAF inhibition in V600E-mutated melanoma cells, and amplification of cyclin D1 is detected in ~17% of BRAF V600E-mutated human metastatic melanomas." (PMID 26201960, 2015). "It was interesting that eleven of the molecules previously implicated in melanoma pathogenesis (described in the introduction) were identified as hubs in the Bayesian gene networks generated from our A375 cell dataset, including: BRAF, CCND1, RB1, PTEN, TYR, CDKN2A, and SOX10." (PMID 22536322, 2012). "The combination of MEK and ERK inhibitors suppresses the expression of cyclin‐D1, enhances the apoptosis, and inhibits the growth of BRAF mutant, NRAS mutant, and wild‐type melanoma." (PMID 41492362, 2026). "RI treatment led to the downregulation of CCND1, MYC, and BCL2 in proliferative cell lines, further supporting the role of NSD2 in melanoma progression." (PMID 40386826, 2025). "CCND1 and CDK4, key cell cycle regulators, are often overexpressed in melanomas, leading to uncontrolled cell proliferation." (PMID 40867317, 2025). "Overexpression of FOXF1 adjacent non-coding developmental regulatory RNA (FENDRR) reduces cyclin E1, cyclin D1, CDK4, and CDK6 levels, which arrests melanoma cells in the G1 phase." (PMID 41463281, 2025). "Melanoma: In melanoma, FABP7 knockdown reduces the proliferation and migration of SK-MEL-23 cells, cyclin D1 expression, and Wnt/β-catenin activity." (PMID 40717587, 2025). "The Q1 cohort demonstrated significantly elevated expression of CCNA2, CCNB1, CCND1, and CDH2, indicating CDC25A’s potential regulatory role in coordinating melanoma cell cycle progression with EMT dynamics." (PMID 40216745, 2025). "BNCT treatment of melanoma cells resulted in marked changes in the extracellular matrix (ECM) and decreased cyclin D1 levels, indicating that necrosis, apoptosis, and cell cycle arrest were involved in the observed cell death." (PMID 41477294, 2025). "They showed that treatment of cells with both drugs reduce the expression levels of cyclin D1, CDK4 and CDK6 in melanoma cells, and their results are consistent with those of our study." (PMID 41373567, 2025). "Consistent with the reduced YAP1 KO tumor size and weight, the number of melanoma cells (α-SMA-negative, α-SMA-) that were Ki67-positive (Ki67+) and the number of cyclin D1-positive (cyclin D1+) cells were both decreased in YAP1 KO melanomas." (PMID 38308096, 2024). "Subsequently, these sets were modified to 9p21 (CDKN2A), 6p25 (RREB1), 11q13 (CCND1), and 8q24 (MYC), improving the discriminatory power in differentiating melanomas from nevi." (PMID 38247727, 2024). "The cyclin D1-Cyclin-Dependent Kinases 4 and 6 (CDK4/6) complex is crucial for the development of melanoma." (PMID 39695080, 2024). "The MAPK pathway has been experimentally shown to regulate cyclin D1 in melanocytes and BRAFV600E superficial spreading melanoma, however, the connection between MAPK activity and cyclin D1 expression has not yet been established in ALM." (PMID 38066089, 2024). "In contrast to BRAFV600E melanoma cell lines, CRC cell lines present higher activity of PI3K/AKT pathway and lower levels of phosphorylated MEK, ERK, RSK, cyclin-D1 and Myc." (PMID 37920169, 2023). "Despite DNA damage, cell proliferation markers CCND1 and CCND2 were moderately upregulated in treated normal skin cells but downregulated in treated melanoma cells." (PMID 36241419, 2023). "Immunoblots showed a concentration-dependent decrease of cyclin D1 and CDK4 expression level in melanoma cells treated for 24 h with HPF." (PMID 36674794, 2023). "In this study, we aimed to evaluate melanocytic tumors with spitzoid morphology using conventional melanoma FISH (RREB-1, CCND1, MYB and CEP6) and 9p21 FISH (CDKN2A) probes and compare the probe results with clinical and histopathological features." (PMID 38031947, 2023).
melanoma (continued). "Inhibition of the JNK and p38 pathways in MTAP-ANRIL melanoma cells increased the expression level of E-cadherin but decreased the expression levels of SNAIL1, N-cadherin, cyclin B1 and cyclin D1 that were increased by MTAP-ANRIL." (PMID 37277447, 2023). "As a result, a number of studies using conventional melanoma FISH probes (RREB1, CCND1, MYB, CEP6) have been performed in recent years." (PMID 38031947, 2023). "We analyzed 39 cases of atypical Spitz tumor (AST), 10 cases of melanomas with spitzoid features for clinicopathological data and chromosomal alterations, targeting RREB-1 (6p25), CCND1 (11q13), MYB (6q23), together with 9p21 (CDKN2A), using FISH methodology." (PMID 38031947, 2023). "In fact, by targeting genes such as Cyclin C, Cyclin D1, and CDK4, miR-206 functions as a cell-cycle regulator and tumor suppressor in multiple melanoma cell lines." (PMID 35804995, 2022). "An investigation of the relationship between CCND1 amplification and ICI treatment response rate reported a significantly shorter OS, especially in urothelial carcinoma (HR = 3.6) and melanoma (HR = 1.6–2.5)." (PMID 35884537, 2022). "The WB assay result showed that overexpression of RAI14 in knockdown melanoma cell lines partially restored the expression of CDK4 and CCND1." (PMID 36233342, 2022). "The increased levels of Cyclin D1 and the hyperactivation of FAK1 signaling upon Ambra1 depletion have been previously correlated to boosted proliferative rate and invasiveness of melanoma, respectively." (PMID 36243772, 2022). "In conclusion, PCDH9, which is regulated by the circ 0084043-miR-134-5p axis, can suppress malignant biological behavior in melanoma and influence the expression levels of Pyk2, RAC1, Cyclin D1, MMP2, and MMP9." (PMID 36387162, 2022). "The genetic manipulation of Fbxo4 successfully alters the stability of cyclin D1 protein, which is evidenced by the accumulation of cyclin D1 protein in human ESCC tissues and melanoma cells with defective Fbxo4." (PMID 35565262, 2022). "Conversely, CYLD expression has been suggested to be downregulated because of elevated SNAIL1 expression, resulting in increased levels of CCND1(Cyclin-D1) and CDH2 (N-Cadherin) and enhanced proliferation, migration, and invasion of human melanomas." (PMID 35884430, 2022). "Therefore, avoiding ICIs and antiangiogenic agents, while employing CDK4/6 inhibitors alone or in combination with ICIs, and targeting oxidative and lipid metabolism pathways, may be effective therapeutic strategies for melanoma patients harboring CCND1 amplification." (PMID 35844619, 2022). "Our data demonstrate that CCND1 amplification is a stronger prognostic factor for outcomes following immunotherapy in melanoma than TMB and indicate that CCND1 amplification dramatically reduces patient survival regardless of the use of ICIs or TMB." (PMID 35844619, 2022). "The CCND1 and CDK4 genes are found to be altered in a minority of melanomas, representing less than 5%, and depend on the melanoma type." (PMID 34571969, 2021). "HuR-NP treatment significantly diminished protein expression of HuR, Cyclin D1, Cyclin E1, BCL-2, HIF1-α, VEGEF-A, and an increased expression of p27 at both 24 h and 48 h in melanoma cell lines (p < 0.05)." (PMID 33418925, 2021). "For this purpose, we evaluated 61 acral melanomas for CCND1 copy number alteration and cyclin D1 expression." (PMID 34225728, 2021). "To examine the function of p75NTR‐FL/CTF in melanoma, we quantified the mRNA levels of cell‐cycle effectors, including cyclin‐dependent kinase 2 (CDK2), CDK4, cyclin D1, cyclin B1 and cyclin‐dependent kinase 1 (cdc2), by quantitative RT‐PCR (qRT‐PCR)." (PMID 33247998, 2021). "Cyclin D1, CDK6, and CDK4 are significantly downregulated in human melanoma cells after ASNS depletion while p21, a CDK inhibitor, is obviously upregulated in response to ASNS knockdown." (PMID 34540668, 2021).
melanoma (continued). "We examined increases in CCND1 copy number with fluorescence in situ hybridization (FISH), and examined cyclin D1 protein expression with IHC in 61 acral melanomas." (PMID 34225728, 2021). "According to our data, the protein levels of β-catenin and its downstream factors cyclin D1, c-Myc, MMP2, and MMP7 were all markedly decreased in melanoma cells after DHC treatment." (PMID 33833997, 2021). "It was demonstrated that cordycepin inhibited the proliferation of B16-BL6 mouse melanoma cells by stimulating adenosine A3 receptors followed by glycogen synthase kinase (GSK)-3β activation and cyclin D1 inhibition." (PMID 33172093, 2020). "In this study, we aimed to evaluate the diagnostic value of four-color fluorescence in-situ hybridization (FISH) probes specific to the RREB1,CCND1,and MYB genes, and centromere of chromosome 6, in distinguishing DN and melanoma." (PMID 32393283, 2020). "Immunofluorescence staining confirmed inhibition of cyclin D1 and CDK4 in melanoma A375 cells exposed to L-KYN." (PMID 33114713, 2020). "XL888 efficiently reduced levels of ARAF, CRAF and cyclin D1, and inhibited AKT, ERK1/2 and S6 activity in resistant melanoma cells." (PMID 31659567, 2020). "Likewise, 5-aminolevulinic acid-mediated sonodynamic therapy (ALA-SDT) treated melanoma cells showed increased intracellular ROS levels and miR-34a expression, which acted synergistically to inhibit the expression of pro-proliferative factors Cyclin D1 and CDK6 to suppress cell cycle progression." (PMID 35006436, 2020). "Eleven percent cyclin D1 amplification, including 17% of B-RAF V600E melanoma is seen in melanoma, that suggests a potential role of cyclin D1 in intrinsic resistance to B-RAF inhibitors." (PMID 32198408, 2020). "Patient-derived xenograft models (PDX) were performed to detect the effects of CDK4/6 inhibitors on the proliferation of mucosal melanoma cells with altered copy number of CDK4 pathway (CDK4, Cyclin D1 and P16INK4a)." (PMID 31358010, 2019). "Paraffin-embedded nuclei from 262 melanoma tissue sections were assessed for amplification in all five candidate genes (MITF, EGFR, CCND1, cMET, and cKIT)." (PMID 29492214, 2018). "Knockdown of RTL1 in melanoma cells resulted in cell proliferation suppression; cell cycle arrest at G1 phase; and down-regulation of E2F1, CYCLIN D1, cyclin-dependent kinase 6 (CDK6) and c-MYC." (PMID 29285312, 2017). "In the present study, OL decreased the HFD-induced expression of CDK4/cyclin D1, inhibited HFD-induced reduction of apoptotic cell numbers, and inhibited the HFD-induced decreases in the levels of cleaved PARP in B16F10 melanoma tumor tissues." (PMID 28410190, 2017). "The effect of itraconazole treatment on the expression of cyclin D1 was determined in A375 and SK-MEL-28 melanoma cell lines at 48 hours." (PMID 28212537, 2017). "The expression of cyclin D1, collagen XVII and Topoisomerase 2α was high in borderline lesions and in melanomas with a Breslow thickness >1 mm and high mitotic index, and lower in common and blue nevi." (PMID 27461275, 2016). "Ectopic expression of miR-25 in melanoma cells induced β-catenin accumulation in nuclear and inhibited TCF4 (T cell factor 4) activity, as well as the expression of c-Myc and Cyclin D1." (PMID 27801786, 2016). "Taken together, these data suggest that CoQ0 treatment also promotes cell growth inhibition by inducing G1/S transition phase arrest, followed by the down-regulation of cyclin D1/E and CDK4 expression in melanoma cells." (PMID 26968952, 2016). "In our tumor grafting experiment, B16F10; bcat/Fb melanoma tumors showed upregulated expression of cyclin D1 and decreased expression of CDK inhibitor p16 as compared with B16F10; Fb melanoma." (PMID 27061029, 2016). "Next, we examined the effect of CoQ0 on the targets of β-catenin, cyclin D1, survivin, and MMP-9 by immuhistochemicals analysis of B16F10 melanoma xenografted tumor tissues." (PMID 26968952, 2016).
melanoma (continued). "We suggest that CoQ0 exhibit anti-proliferative effect through modulating β-catenin and its downstream target genes, c-myc, cyclin D1, and survivin in B16F10 melanoma cells." (PMID 26968952, 2016). "It significantly reduced the transcript levels of LEF1, WNT10B, MITF-M, c-MYC and CCND1 and increased the mRNA levels of FZD7 and DKK1 in all melanoma cell populations." (PMID 27351373, 2016). "miR-25 activated the WNT pathway by targeting DKK3, thus not only enhancing the ability of melanoma to infiltrate into tumor tissue but also facilitating tumor invasion and metastasis by upregulating TCF4, c-Myc, and Cyclin D1 in vitro and in vivo." (PMID 27801786, 2016). "The BRAF mutation in melanoma drives enhanced proliferation through MAPK-induced expression of cyclin D1 and mediates BRAF inhibitor resistance in melanoma cells." (PMID 26299806, 2015). "We also found that few well-known melanoma biomarkers like NRAS, CDK4 and CCND1 are significantly rewired in different metastatic melanoma stages, even if not differentially expressed (in the particular stage)." (PMID 26558755, 2015). "We predicted through quantitative simulations that melanoma cells were arrested in G1-phase of the cell cycle when c-Myc was targeted alone or in combination with other proteins, particularly BRAF, MEK, and cyclin D1." (PMID 26284497, 2015). "A recent study of miR-206 in melanoma showed that it targeted CDK4, Cyclin C and Cyclin D1 which were cell cycle genes." (PMID 25255814, 2014). "Array CGH results were further confirmed by four colour FISH experiments specific for 11q13 (specific for CCND1 gene), 6p25 (specific for RREB1 gene), 6q23 (specific for MYB gene) and centromere 6 on 27 primary melanomas." (PMID 24832207, 2014). "Next, we searched for CNAs in genes known to be affected by CNAs in melanoma (BRAF, KIT, MITF, CCND1, CDK4, PTEN, CDKN2A and AKT3)." (PMID 24399611, 2014). "Increase of CYCLIN D1 and CDK4 proteins in melanoma cells can also be a consequence of gene amplification." (PMID 21860617, 2012). "Thus, what more could be responsible for CYCLIN D1/CDK4 increase in melanoma cells?" (PMID 21860617, 2012). "In melanoma cells, p38-ATF-2-dependent expression of cyclin D1 in response to hepatocyte growth factor/scatter factor has been described." (PMID 22404972, 2012). "In NRAS‐mutated melanoma, S6 phosphorylation mainly depends on RSK rather than S6K1, and dysregulation of phosphorylation S6 leads to upregulation of cyclin D1 (CCND1) and inactivation of the tumor suppressor p16 [INK4A68]." (PMID 41492362, 2026). "This study suggested that combined MEK inhibitor with CDK4/6 inhibitor may be clinically more active in NRASmut melanoma patients with concurrent genetic alterations (such as CDKN2A, CDK4, or CCND1) in G1 cell‐cycle checkpoint than MEK inhibition alone." (PMID 41492362, 2026). "Moreover, the expression and nuclear accumulation of cyclin D1 and p21 were also suppressed in AZD6244-treated BRAF PTEN PREX2 melanomas (right)." (PMID 39636745, 2025). "Notably, various third-generation, FDA-approved cyclin D1/CDK inhibitors such as palbociclib, ribociclib, and abemaciclib are currently undergoing preclinical studies in patients with melanoma." (PMID 39948552, 2025). "Immunohistochemically, the tumor cells were positive for S100 (5/6), cyclin D1 (2/3), SATB2 (2/3), BCOR (2/4), and TLE1 (1/3) while negative for MUC4 (0/6), keratin (0/5), EMA (0/4), desmin (0/6), CD34 (0/6), SMA (0/5), SOX10 (0/5), and pan melanoma (0/2)." (PMID 40705064, 2025). "The observed changes in the expression of the CCND1 and CDKN1B genes may indicate their possible impact on cell cycle arrest and decreased melanoma cells proliferation potential." (PMID 41373567, 2025).